LYPD5 (LY6/PLAUR domain containing 5)
Synonyms: FLJ30469; Haldisin; PRO4356
Tractability: Antibody: UniProt places it where antibodies can reach, with high confidence; its Gene Ontology location is reachable by antibodies, with high confidence; UniProt predicts a signal peptide or a membrane-spanning region.
Gene: Protein-coding gene on chromosome 19 (43,785,874 to 43,827,206, reverse strand). Ensembl gene ENSG00000159871.
Subcellular location: Cell membrane
Subcellular location (Human Protein Atlas): Cytosol; Nucleoplasm
Pathways (Reactome):
Metabolism of proteins: Post-translational modification: synthesis of GPI-anchored proteins
Gene Ontology:
Molecular function: protein binding
Cellular component: extracellular region; plasma membrane
Genetic constraint (gnomAD): Loss-of-function variants: 21 observed, 19.11 expected, observed/expected ratio (o/e) 1.1, 90% interval 0.78 to 1.58. The upper end of that interval is the gene's LOEUF score, 1.58, which puts it in group 6 of 6, group 1 being the genes least tolerant of losing a copy. Missense variants: 287 observed, 321.92 expected, observed/expected ratio (o/e) 0.89, 90% interval 0.81 to 0.98. Synonymous variants: 128 observed, 132.99 expected, observed/expected ratio (o/e) 0.96, 90% interval 0.83 to 1.12.
Homologues: Orthologues: chimpanzee LYPD5 (99% identical), macaque LYPD5 (95% identical), pig LYPD5 (73% identical), dog LYPD5 (73% identical), mouse Lypd5 (71% identical), rat Lypd5 (70% identical), guinea pig LYPD5 (55% identical). Paralogues in human: LYPD3 (29% identical), PLAUR (20% identical).
Diseases named in the same sentence as LYPD5 in open-access papers:
LYPD5 is named in the same sentence as 12 diseases in open-access papers, as found by Europe PMC text mining. Sharing a sentence is not in itself a finding about the gene and the disease.
LYPD5 shares sentences with these, for which no sentence is quoted: cancer (13 papers); tumor (10); breast carcinoma (8); prostate carcinoma (3); colon cancer (2); gastric cancer (2); lymph node metastasis (1); metastatic tumors (1); non-small cell lung carcinoma (1); Osteochondroma (1); ovarian serous cystadenocarcinoma (1); pancreatic cancer (1).